EGFR (epidermal growth factor receptor)
Diseases named in the same sentence as EGFR in open-access papers (continued):
Sharing a sentence is not in itself a finding about the gene and the disease.
glioblastoma (continued). "Two fusions identified as having oncogenic potential in our study had previously been associated with glioblastoma: FGFR3::TACC3 and EGFR::SEPTIN14." (PMID 36002559, 2022). "In this study, we discovered widespread chromatin organization alterations of EGFR-amplified glioblastoma at the compartment, TAD, and loop levels, which contribute to oncogene activation and tumor repressor deactivation in EGFR-amplified glioblastoma." (PMID 35521558, 2022). "They discovered that epidermal growth factor receptor (EGFR) activation plays a role in m6A modification in glioblastoma and YTHDF2 overexpression occurred through the EGFR/SRC/ERK pathway." (PMID 35625706, 2022). "We constructed glioblastoma cell lines stably expressing wild-type EGFR and the mutant of EGFR S645C." (PMID 35814475, 2022). "The loss of extrachromosomal DNA EGFRvIII is a common and clinically relevant EGFR TKI resistance mechanism in glioblastoma multiforme." (PMID 35494014, 2022). "Epidermal growth factor receptor is upregulated in most glioblastoma tumours and, therefore, has been a drug target in recent targeted therapy clinical trials." (PMID 36497413, 2022). "In almost forty percent of IDH-wild-type glioblastomas, EGFR amplification is observed, and 1/2 of these tumors also harbor a genetic rearrangement which leads to the removal of EGFR exons 2–7." (PMID 35989351, 2022). "The two aptamers were then used to detect EGFR and integrin α5β1 in human glioblastoma tissues and compared with antibody labeling." (PMID 36297416, 2022). "For IDHwt glioblastomas, 2021 WHO Classification identifies that TERT promoter mutations and EGFR alterations are characteristically found." (PMID 36380219, 2022). "Then, we analysed tumor DNA samples from 19 IDH-wildtype glioblastomas with known EGFR status (samples 26–44)." (PMID 35361262, 2022). "Atypical EGFR signaling in glioblastoma activates the transcription factor IRF3, leading to the expression of IFI27, which often plays an important oncogenic role." (PMID 36291283, 2022). "Another mafodotin-based ADC is depatuxizumab mafodotin, whose antibody (mAb 806) targets a unique tumor-specific epitope of EGFR and is currently being employed in several clinical trials in patients with glioblastoma or with EGFR-overexpressed solid tumors." (PMID 36005497, 2022). "As is the case with EGFR amplification, diffuse gliomas formerly classified as IDH-wildtype grade 2–3 diffuse astrocytomas with TERT promoter mutations are now classified as glioblastomas, IDH-wildtype." (PMID 35693015, 2022). "We investigated the combined effects of erlotinib and luteolin on proliferation and apoptosis on glioblastoma cell lines overexpressing EGFR or glioma cells expressing truncated EGFR (ΔEGFR)." (PMID 36199696, 2022). "Future studies are needed to further explain the interplay between genetic, epigenetic, 3D genome, and transcription for specific oncogenes in EGFR-amplified glioblastoma." (PMID 35521558, 2022). "The 3D chromatin organization of the EGFR-amplified glioblastoma-derived A172 genome is altered at various levels." (PMID 35521558, 2022). "EGFR amplification and overexpression are two of the most frequently seen genetic alterations in glioblastoma." (PMID 35053605, 2022). "In particular, a phase II trial involving patients with EGFR-activated glioblastoma is evaluating the effect of osimertinib on tumor cell growth by blocking enzymes required for cell growth." (PMID 35888045, 2022).
glioblastoma (continued). "A phase II/III study (NCT02573324) was currently underway in participants with newly diagnosed glioblastoma with EGFR amplification." (PMID 35295841, 2022). "Patients with EGFR-amplified, relapsed glioblastoma were included in this phase I pharmacokinetic trial." (PMID 34998092, 2022). "Machine learning algorithms for program-controlled, non-invasive detection of radiogenomic markers in IDH and EGFR in low-grade gliomas and glioblastomas showed success rates of over 80%." (PMID 35330402, 2022). "MicroArray-profiling analysis revealed upregulation of the miR-183/96/182 cluster in EGFR-amplified glioblastoma, comprising the mature miRs 183-5p, 96-5p, and 182-5p." (PMID 35486213, 2022). "We end the review with a focus on high grade gliomas, primarily glioblastoma, a disease that has been shown to involve EGFR and its mutant forms." (PMID 36119496, 2022). "It has been found that the oncogene EGFR often co-amplifies with upstream enhancers and forms ecDNA in glioblastoma, generating new enhancer-oncogene contacts and promoting tumour progression." (PMID 35844796, 2022). "We further investigated the effects of these drug combinations on EGFR downstream cell signaling proteins as they play an essential role in glioblastoma invasive growth." (PMID 36199696, 2022). "EGFR is a significant cancer marker for diagnosis and a promising target for the treatment of glioblastoma, a malignant brain tumor." (PMID 36615487, 2022). "EGFR alterations have been linked to glioblastoma, and tumors previously defined as diffuse grade 2–3 astrocytoma, IDH wildtype are currently considered glioblastomas if they harbor EGFR amplification." (PMID 35693015, 2022). "In this study, we performed fluorescence imaging with two aptamers targeting cell-surface receptors EGFR and integrin α5β1, both involved in the aggressiveness of glioblastoma." (PMID 36297416, 2022). "It has been reported that the conjugation of gold nanoparticle with Cet selectively bind to EGFR, and then induce internalization on EGFR overexpressing glioblastoma cells." (PMID 36678740, 2022). "An example of glioblastoma dormancy regulators include the epidermal growth factor receptor (EGFR) and thrombospondin (TSP)." (PMID 36430404, 2022). "In this frame, SPION were coupled with an anti-EGFR antibody, which was expressed in human glioblastoma multiforme (GBM), and then used for MRI directed CED in cancer therapy." (PMID 35054340, 2022). "For solid tumors, anti-HER2 and anti-EGFR engineered-NK therapy have been reported in several cancers like glioblastoma, breast, and ovarian cancers." (PMID 36324149, 2022). "Amplification of EGFR is noted in over 50% of glioblastoma cases, and has tumor-promoting effects on multiple downstream signaling pathways that are linked to proliferation, angiogenesis, fatty acid synthesis, infiltration, and apoptosis." (PMID 35456993, 2022). "We aimed to explore the treatment of patients with EGFR-amplified glioblastoma with EGFR-targeted immunoliposomes containing doxorubicin." (PMID 34998092, 2022). "The signals of exosomes from Glioblastoma patients were significantly higher than healthy samples, being consistent with the higher expression of EGFR in Glioblastoma-derived exosomes than normal cells." (PMID 35281563, 2022). "First, the high surface expression of epidermal growth factor receptor (EGFR) in glioblastoma patient tissue and cell lines was confirmed using immunohistochemistry staining, flow cytometry, and Western blotting." (PMID 35052809, 2022). "verified reciprocal control of ADAM17/EGFR/Akt signaling and miR-145 drives glioblastoma multiforme (GBM) invasiveness." (PMID 36033536, 2022). "Recently, it has been shown that glioblastomas with active EGFR signaling are particularly reliant on the glucose-6-phosphate dehydrogenase." (PMID 36230918, 2022).
glioblastoma (continued). "In summary, this study shows an upregulation of the miR-183/96/182 cluster in EGFR-amplified glioblastoma, accompanied by reduced expression of FOXO1." (PMID 35486213, 2022). "Epidermal growth factor receptor (EGFR) is a transmembrane tyrosine kinase overexpressed in human glioblastoma, thus representing a promising target for BSH selective delivery." (PMID 36552793, 2022). "NF-κB is constitutively overexpressed in glioblastoma and its aberrant activation is connected to EGFR deregulation (which promotes tumor cell proliferation and survival) and the PI3K/Akt/mTOR signaling pathway." (PMID 35328780, 2022). "In this study, we have used extensively EGFR amplification and 10q loss in addition to TERT, as 10q loss has been shown to be associated with glioblastomas for many years." (PMID 35558510, 2022). "Recent reports in glioblastoma have demonstrated that asymmetric enrichment of EGFR and p75NTR in a daughter cell during cell division conferred enhanced resistance to the standard-of-care therapies, such as radiation and temozolomide." (PMID 35327538, 2022). "To preserve large intact circular ecDNA, we encapsulated genomic DNA of GBM39 cells (patient-derived glioblastoma neurosphere model containing EGFR ecDNA) in agarose plugs." (PMID 36253572, 2022). "EGFR promotes lipogenesis in cancer cells, for instance, in glioblastoma cell lines, EGFR-enhanced SREBP-1 cleavage, and nuclear translocation via EGFR-PI3K-Akt pathway." (PMID 36360201, 2022). "The last hub lncRNA NEAT1 promotes glioblastoma development and progression through the EGFR/NEAT1/EZH2/WNT/β-catenin axis." (PMID 36090045, 2022). "LncRNA PITPNA-AS1 inhibits apoptosis of glioblastoma cells by upregulating epidermal growth factor receptor (EGFR) expression and phosphorylating AKT." (PMID 36230902, 2022). "In glioblastoma specifically, harmine suppresses EGFR-dependent growth through the inhibition of the dual-specificity tyrosine-(Y)-phosphorylation-regulated kinase, DYRK1A." (PMID 35456993, 2022). "Yi and colleagues independently identified ecDNA hubs in multiple EGFR-amplified glioblastoma neurosphere lines from both primary and recurrent tumors." (PMID 35398879, 2022). "Using immunohistochemistry for EGFRvIII corroborated the presence of EGFRvIII-positive tumor cells in these two tumors as well as four additional glioblastomas with EGFR amplification." (PMID 35361262, 2022). "In glioblastomas, EGFR and two related enhancers are in a 480 kb circular domain, co-amplification of EGFR with enhancers results in a dramatic change in the interaction pattern between the EGFR promoter and several adjacent cis-regulatory elements." (PMID 35494014, 2022). "In glioblastoma multiforme (GBM), the uPAR interacts with a truncated variant of EGFR, supporting tumor cell survival and growth." (PMID 35493073, 2022). "The disordered 3D genomic map and multi-omics data of EGFR-amplified glioblastoma provide a resource for future interrogation of the relationship between chromatin interactions and transcriptome in tumorigenesis." (PMID 35521558, 2022). "In adult glioblastomas, the highest levels of CD73 are associated with EGFR activation and astrocyte-like differentiation, whereas in pediatric gliomas CD73 expression is linked to PDGFRA activation and OPC-like differentiation." (PMID 35973991, 2022). "Unfortunately, glioblastoma cells are insensitive to EGFR tyrosine kinase inhibitors (EGFR-TKIs), creating a dilemma for drug treatment." (PMID 36010960, 2022). "Up to 60% of glioblastoma tumours have increased activity of a growth factor called epidermal growth factor receptor, which drives tumour growth." (PMID 36497413, 2022). "There have been several EGFR gene alterations identified in gliomas, especially in glioblastomas, which acted as a prognostic factor and a predictor of treatment response in patients with glioma." (PMID 36698888, 2022).
glioblastoma (continued). "The reshaped chromatin conformation in glioblastoma cells contributed to the upregulation of EGFR by exploiting enhancers from flanking TAD." (PMID 35521558, 2022). "To investigate the TAD alteration pattern of EGFR-amplified glioblastoma, we compared the TAD boundaries of A172 and HA1800." (PMID 35521558, 2022). "This is the first multi-omics dataset comparing histologically homologous EGFR-amplified glioblastoma with astrocytes, which provides a valuable resource for future of the relationship between chromatin interactions and transcriptome in tumorigenesis." (PMID 35521558, 2022). "FGFR3-TACC3 fusions were mutually exclusive with EGFR-amplifications, a mutation that is present in about 80% of IDH-wildtype glioblastoma." (PMID 35955806, 2022). "The frequency of reported EGFR amplification is highly variable (8–50%) and is influenced by many parameters including ethnicity and glioblastoma subtype." (PMID 35324914, 2022). "Overexpressed EGFR, which was seen in 22–89% of glioblastomas, disrupts downstream signalling pathways, including PI3K, Akt, and MAPK." (PMID 35214064, 2022). "The altered chromatin structure of EGFR-amplified glioblastoma shows increased distance from nuclear periphery to the center, elevated chromatin relaxation, and unexpected entanglement of chromosome territories." (PMID 35521558, 2022). "We clearly demonstrate that anti-EGFR-immunoliposomes can be targeted to EGFR-amplified glioblastoma and cargo—in this case doxorubicin—can be delivered, although these immunoliposomes do not cross the intact BBB." (PMID 34998092, 2022). "Genomic and transcriptomic analysis of anti-EGFR CAR T cell-treated glioblastoma cells showed an upregulation of genes for inhibitory immune checkpoints, inflammatory cytokines, and immunosuppressive molecules, limiting CAR T cell efficacy." (PMID 35203517, 2022). "The genes most involved in fusions in IDH wild-type glioblastoma are EGFR (6–13%), FGFR3 (3%), MET (1–4%) and the NTRK gene family (1–2%)." (PMID 36002559, 2022). "Epidermal Growth Factor Receptor (EGFR) is amplified in over 50% of glioblastomas and promotes tumor formation and progression." (PMID 35456993, 2022). "For example, in glioblastoma, epidermal growth factor receptor (EGFR) is expressed by the tumor-specific mRNA EGFRvIII, which was recommended as a diagnostic biomarker for glioblastoma." (PMID 35269604, 2022). "In a phase 1/2 trial, the median survival of newly diagnosed glioblastoma patients who underwent radiation therapy with gefitinib, an EGFR inhibitor, was similar to the survival of the control group receiving radiation alone." (PMID 36135196, 2022). "For example, the rolling-translated EGFR protein translated from circEGFR consistently activates oncogenic EGFR signaling by sustaining EGFR membrane localization in glioblastoma." (PMID 36814375, 2022). "EGFRvIII-specific CAR-T cells were unable to completely treat tumors with heterogeneous EGFRvIII expression, leading to outgrowth of EGFRvIII-negative, EGFR-positive glioblastoma." (PMID 36578789, 2022). "Many preclinical studies have been described with QDs, for instance targeting epidermal growth factor receptor (EGFR) with multifunctional siRNA-QD constructs for selectively inhibiting the expression of EGFRvariant III in target human U87 glioblastoma cells." (PMID 35159744, 2022). "In general, 40–50% of patients with glioblastomas also show overexpression and augmentation of EGFR." (PMID 35592520, 2022). "ABT-414 was found to retain the excellent binding and functional properties of ABT-806, and exhibit significant efficacy against glioblastoma patient-derived xenograft models with either wild-type EGFR or mutant EGFR overexpression." (PMID 35295841, 2022). "We assessed the capacity of epidermal growth factor receptor (EGFR)-targeted immunoliposomes to deliver cargo to brain tumor tissue in patients with relapsed glioblastoma harboring an EGFR amplification." (PMID 34998092, 2022).
glioblastoma (continued). "EGFR mRNA is a validated target of miR-491-5p in other types of cancers, such as glioblastomas and ovarian carcinomas." (PMID 35337159, 2022). "The present study was undertaken to evaluate GZ17-6.02, a novel anti-cancer agent which is currently undergoing phase I trials in various cancers, for its growth inhibition of glioblastomas expressing a specific form of EGFR, namely EGFRvIII." (PMID 35456993, 2022). "ABT-806 is the parent antibody of ABT-414, an antibody-drug conjugate (ADC) developed to engage EGFR-overexpressing glioblastoma (GBM) tumor cells." (PMID 35890344, 2022). "Here, we characterize a unique subgroup of CSCs in MGMT-null experimental glioblastoma, identifying EGF + TMZ therapy as a potential strategy to overcome cellular quiescence and TMZ resistance, likely endowed by deficient EGFR signaling." (PMID 36316307, 2022). "ANXA7 has been shown to downregulate EGFR in glioblastoma and loss of ANXA7 mRNA expression was associated with poor survival and prognosis in glioblastoma patients." (PMID 36247003, 2022). "The expressions of the epidermal growth factor receptor (EGFR) EGFRvIII are remarkably high in the serum samples of glioblastoma patients in contrast to that of healthy individuals." (PMID 35163563, 2022). "The INTELLANCE 2/EORTC 1410 phase 2 trial produced interesting results for the combination regimen of Depatux-M and temozolomide in EGFR-amplified glioblastoma patients at first recurrence." (PMID 34204877, 2021). "Consistently, we recently demonstrated that the endosomal pathway of α5β1 dimer in glioblastoma overlaps that of EGFR in response to gefitinib." (PMID 34831480, 2021). "The phosphatidylinositide 3-kinase (PI3K) pathway is frequently overactivated in glioblastoma due to PIK3CA mutations, loss of phosphotase and tensin homolog (PTEN) gene function, and amplification of epidermal growth factor receptor (EGFR) gene expression." (PMID 34899305, 2021). "Our findings suggest that EGFR signaling is involved in AR activation in glioblastoma and buttresses the concept of combining an EGFR signaling inhibitor with AR antagonists as a potential glioblastoma treatment." (PMID 34681618, 2021). "EGFR is hyperactivated by mutations in about 10% of NSCLC patients and by gene amplification in an even larger fraction of glioblastoma patients." (PMID 33777943, 2021). "DYRK1A inhibition promoted EGFR degradation in glioblastoma cells, which sharply reduced the self-renewal and proliferation of cancer cells." (PMID 33500384, 2021). "This approach has been shown to be efficacious in Glioblastoma preclinical mouse models using an EGFRvIII-targeting CAR T-cell modified to secrete EGFR BiTEs in the tumor microenvironment." (PMID 33936101, 2021). "Combined with a BiTE specific for the wild-type EGFR, which is frequently overexpressed in glioblastoma, BiTE co-expression has the potential to recruit bystander cells and redirect them against wild type EGFR, thus resulting in complete tumour control." (PMID 34885108, 2021). "Glioblastoma cells in hypoxic regions of tumors overexpress the epidermal growth factor receptor, and the vascular regions express the platelet-derived growth factor receptor α33." (PMID 34086429, 2021). "Correlation between the imaging signature and EGFR amplification (AUC=0.86, p<0.0001), O6-methylguanine-DNA-methyltransferase methylation/expression (AUC=0.92) and glioblastoma molecular subgroups (AUC=0.88) was derived." (PMID 34164563, 2021). "Taken together, amplification of LANCL2 and EGFR were the independent diagnostic biomarkers for glioblastoma patients, and LANCL2 amplification was a significant prognostic factor for OS in younger glioblastoma patients." (PMID 34461927, 2021). "Anti-EGFR Nbs (ENb) have also been produced and secreted from stem cells for glioblastoma multiforme (GBM) therapy." (PMID 34575943, 2021).